NR4A1 (nuclear receptor subfamily 4 group A member 1)
Diseases named in the same sentence as NR4A1 in open-access papers (continued):
Sharing a sentence is not in itself a finding about the gene and the disease.
hemorrhage (1 paper, 2020). Loss of blood from the vascular compartment to the exterior or into nonvascular body space as a result of rupture or severance of the blood vessels. "Notably, the incidence of hemorrhage in Nr4a1 KO brains exposed to LPS and MgSO4/BMTZ was greater versus wt counterparts and similar to mutant mice that received only LPS." (PMID 31907354, 2020).
Hypocholesterolemia (1 paper, 2025). An decreased concentration of cholesterol in the blood. "Using human NR4A1 expression data and platelets from patients with hypocholesterolemia and mouse models, it was demonstrated that loss of NR4A1 (in mice) enhanced thrombus formation, microvascular microthrombi obstruction, and platelet activation." (PMID 40871737, 2025). "Higher expression of NR4A1 is observed in leukocytes from patients with hypocholesterolemia and in cell culture cholesterol induces NR4A1 and loss of the receptor enhances expression of inflammatory genes such as IL-6 and MCP-1." (PMID 40871737, 2025).
ischemic disease (1 paper, 2019). Lack of blood supply to an area of the body, resulting in impairment of tissue oxygenation. "Surprisingly, F1 and Rh1 can significantly restore VEGF- or Csn-B-induced vascular leakage, suggesting that F1 and Rh1 specifically inhibit NR4A1, which can be an effective therapeutic candidate for blocking vascular leakage in ischemic disease and cancer." (PMID 30872732, 2019).
keratoconus (1 paper, 2025). A degenerative, structural disorder of the eye, characterized by a cone-shaped protrusion of the cornea. "It has been suggested that reduced expression of the steroid-retinoid hormone receptor encoded by NR4A1, is known to be involved in apoptosis and may also be part of a deregulated injury response in keratoconus." (PMID 39420106, 2025).
Klebsiella pneumoniae pneumonia (1 paper, 2025). "Nr4a1-deficient mice are highly susceptible to Klebsiella pneumoniae pneumonia, which was mediated by Nr4a1 expression in immune cells." (PMID 40114913, 2025).
lichen planus (1 paper, 2024). A chronic, recurrent, pruritic inflammatory disorder of unknown etiology that affects the skin and mucus membranes. "The results showed that both CD103 and NR4A1 were increased in the dermis of tumor and patch lesion in advantage-stage MF compared to lichen planus patients." (PMID 39963655, 2024).
mastitis (1 paper, 2022). Inflammation of breast tissue during lactation or postpartum due to an obstructed duct or infection. "Meanwhile, miR-375 modulates mastitis in dairy cows by regulating the expression of NR4A1." (PMID 35681895, 2022).
monocytopenia (1 paper, 2024). "Under steady-state conditions, this process is governed by the transcription factors C/EBPβ and NR4A1, as evidenced by the monocytopenia of NCMs in Cebpb–/– or Nr4a1–/– mice." (PMID 39545417, 2024).
mood disorder (1 paper, 2021). A cognitive disorder a disturbance in which the person's mood is hypothesized to be the main underlying feature. "We quantified mRNA levels corresponding to interneuron marker genes (PV and SST), plasticity genes known to be altered by OTX2 levels (Gadd45b, Arc, Nr4a1), and inflammatory/oxidative stress pathway genes (Mtnd4 and Iba1), given that mood disorders can be related to oxidative stress response." (PMID 33963285, 2021).
myeloproliferative neoplasm (1 paper, 2019). A clonal hematopoietic stem cell disorder, characterized by proliferation in the bone marrow of one or more of the myeloid (i.e., granulocytic, erythroid, megakaryocytic, and mast cell) lineages. "Furthermore, the deletion of NR4A1 and NR4A3 in mice is found to lead to AML13, and redujinction in the gene dosages of NR4A1 and NR4A3 in hypoallelic mice beyond a critical threshold is sufficient to cause mixed myelodysplastic/myeloproliferative neoplasms (MDS/MPN), along with AML progression." (PMID 31839811, 2019).
myosarcoma (1 paper, 2024). "Previous studies show that G9a is an NR4A1-regulated gene in Rhabdo-myosarcoma cells suggesting that kaempferol and other flavonoids may also bind NR4A1." (PMID 38116863, 2024).
nephritis (1 paper, 2025). Inflammation of renal tissue. "Using transcriptome data from the anti-Thy1 nephritis rat model, we finally identified 14 DEGs, among which NR4A1 was significantly downregulated in renal tissues of IgAN." (PMID 41345104, 2025).
Osteopenia (1 paper, 2025). Osteopenia is a term to define bone density that is not normal but also not as low as osteoporosis. "This study successfully identified a subtype of C2 NR4A1+ MSCs with distinct metabolic features and differentiation potential in the bone microenvironment of osteopenia using scRNA-seq." (PMID 41262236, 2025). "Based on the central role of C2 NR4A1+ MSC in the early stages of MSC differentiation, we further investigated their intercellular communication within the osteopenia-associated microenvironment." (PMID 41262236, 2025). "This study utilized scRNA-seq to identify C2 NR4A1+ MSCs with distinct metabolic features and differentiation potential in the bone microenvironment during the early stage of OP, namely, osteopenia." (PMID 41262236, 2025). "In summary, our research indicates that OPC may serve as a potential therapeutic candidate by targeting and regulating C2 NR4A1+ MSCs in osteopenia, thereby playing a role in the prevention and treatment of OP." (PMID 41262236, 2025). "Therefore, focusing on C2 NR4A1+ MSCs not only helped to deepen our understanding of MSC fate determination but also provided clues for identifying critical time windows to intervene in the progression of osteopenia." (PMID 41262236, 2025). "To further analyze the diversity of MSCs in osteopenia and their potential functional differentiation, we conducted a detailed subtype analysis and identified three MSC subtypes with different molecular characteristics and functional states: C1 SIX1+ MSCs, C2 NR4A1+ MSCs, and C3 KLF4+ MSCs." (PMID 41262236, 2025).
prediabetes (1 paper, 2010). "In light of these data, NR4A1 appears to be an attractive prediabetes candidate gene." (PMID 20525362, 2010).
renal clear cell carcinoma (1 paper, 2024). "We recently found that NR4A1 is the most elevated gene in the TI-Tregs from human renal clear cell carcinoma (RCC; GEO: GSE121638)." (PMID 38334978, 2024).
respiratory infections (1 paper, 2017). "Hence, a better knowledge of the interactions of NR4A1 with the immune response should provide insights for the elaboration of new therapeutic strategies to control respiratory infections." (PMID 29053748, 2017).
sclerosing cholangitis (1 paper, 2023). A chronic, autoimmune inflammatory liver disorder characterized by narrowing and scarring of the lumen of the bile ducts. "In conclusion, we demonstrated that activation of NR4a1 via teduglutide improves hepatic inflammation and fibrosis in the Mdr2-/- mouse model of sclerosing cholangitis." (PMID 37572734, 2023). "In the present study we investigated whether treatment with the GLP-2 analogue teduglutide improves liver injury in the Mdr2/Abcb4-/- mouse model of sclerosing cholangitis possibly via activation of NR4a1/Nur77 in HSCs." (PMID 37572734, 2023).
stress-related disorder (1 paper, 2023). Stress-related disorders are mental health disorders that are a result of an atypical response to both short and long-term anxiety due to physical, mental, or emotional stress. "However, evidence exists that other antidepressants, such as vortioxetine and fluoxetine, increased the expression of this gene, further supporting the notion that Nr4a1 may represent a target for the development of novel drugs to treat stress-related disorders." (PMID 37108481, 2023).
substance abuse (1 paper, 2025). The use of a drug for a reason other than which it was intended or in a manner or in quantities other than directed. "Furthermore, transcription factors Nr4a1 and Egr2 have been reported to play important roles in mediating the neurobiology and behavioral consequences of substance abuse, including METH." (PMID 41002437, 2025).
thymic lymphoma (1 paper, 2013). "Conditional deletion of Fbxw7 in CD4+ cells, or deletion of Nr4a3 and the closely related Nr4a1, resulted in hyper-proliferation of T cells, thymic lymphoma's and lethal lymphoproliferation, a phenotype similar to Foxp3−/− mice." (PMID 23825948, 2013).
Tinnitus (1 paper, 2023). Tinnitus is an auditory perception that can be described as the experience of sound, in the ear or in the head, in the absence of external acoustic stimulation. "Down-regulation of the Nr4a1 gene means that noise-induced tinnitus may derive from neural inflammation in the central nervous system." (PMID 37190538, 2023). "The expressions of Fos (p < 0.05), Nr4a1 (p < 0.01), Nr4a3 (p < 0.05), Egr2 (p < 0.01), and Egr3 (p < 0.05) were significantly decreased in the tinnitus group compared to the non-tinnitus group." (PMID 37190538, 2023).
tuberculosis (1 paper, 2026). A chronic, recurrent infection caused by the bacterium Mycobacterium tuberculosis. "Using knockout mice, adoptive-transfer models and validation in macaque and human datasets, we identified the nuclear receptor NR4A1 as a key restrainer of CD8+ T cell immunity in tuberculosis (TB)." (PMID 41646403, 2026).
tumor (2,120 papers, 1990 to 2026). "Cluster 2 expressed Nr4a1, a gene associated with unique glycolytic regulating effects in tumor cells." (PMID 41567211, 2025). "This review explores diverse functions of NR4A1 in tumor-associated immune cells, including T cells, monocytes, natural killer cells, B cells, dendritic cells, macrophages, and neutrophils." (PMID 40508074, 2025). "Similar findings were observed in head and neck squamous cell carcinomas, where the overexpression of NR4A1 in NK cells is linked to impaired NK cell activity and increased tumor progression." (PMID 40508074, 2025). "Together, these results indicate that redox balance disruption exacerbated by NR4A1 deficiency is involved in uncontrolled tumor growth." (PMID 40164686, 2025). "The broader involvement of NR4A1 across different immune cells, such as T, B, and NK cells, underlines its multifaceted roles in the tumor-associated immune response." (PMID 38334978, 2024). "Loss of Kindlin-1 leads to increased tumor growth, with many of the most upregulated genes in the Kindlin-1-depleted tumors linked to cancer prognosis, including Cstf2, Ppp1r10, Nr4a1 and Ggt1." (PMID 38982038, 2024). "Injection of NR4A1-deficient CAR-T cells into mice bearing a tumor can significantly inhibit tumor growth." (PMID 36979400, 2023). "Previous studies have shown that NR4A1 can play a role as a tumour suppressor in association with BNDF." (PMID 36497280, 2022). "The NR4A1 mediator CsnB induced tumor cell apoptosis; this suppressive function of CsnB is associated with the translocation of NR4A1 from the nucleus to mitochondria to release the cytochrome C-depended Bcl-2 apoptotic pathway." (PMID 36052242, 2022). "Several predicted TFs in tumor-reactive cells have been reported to be associated with T cell exhaustion, such as NR4A1 and BATF." (PMID 31892342, 2019). "NR4A1 has been implicated in oncogenesis and tumor suppression, as well as with endoplasmic reticulum stress, in PDAC cells." (PMID 31568691, 2019). "CAR T-cells with deficiencies in Nr4a1, Nr4a2 and Nr4a3 showed improved tumor cell death and increased effector function." (PMID 31683815, 2019). "More importantly, we found that the decreased levels of NR4A1 expression in TNBC are associated with advanced tumor stages, lymph node metastasis and worse relapse-free survival." (PMID 28903348, 2017). "Together, these results suggest that decreased NR4A1 protein in TNBC tumors is associated with increased TNBC progression including more advanced tumor stages, higher metastasis frequency, more recurrence incidence and poorer relapse-free survival." (PMID 28903348, 2017). "The low expression of NR4A1 protein in human TNBC samples is associated with advanced tumor stage, lymph node metastasis and disease recurrence." (PMID 28903348, 2017). "Furthermore, tumor angiogenesis and modulation of genes associated with angiogenesis were critically reduced in tumor tissues treated with NR4A1 shRNAs and selective minigenes." (PMID 33634114, 2021). "Furthermore, the expression levels of NR4A1 in human TNBC were negatively associated with tumor stage, lymph node metastasis and disease recurrence." (PMID 28903348, 2017). "Finally, analysis of metastatic adenocarcinomas of diverse origin and comparison with primary adenocarcinomas of the same tumour spectrum identified NR4A1 as part of a 17-gene signature associated with metastasis as one of the downregulated genes." (PMID 20642837, 2010). "NR4A1 interferes with intracellular regulation at different levels through various signaling pathways associated with many cancers, and understanding these interactions may elucidate the role of this family member in tumorigenesis and tumor suppression." (PMID 40666103, 2025). "Spatial tissue analyses revealed a scarcity of activated T cells near regions with high NR4A1 expression, consistent with an immunosuppressed tumor microenvironment." (PMID 41912809, 2026).
tumor (continued). "Functionally, NR4A1-driven CARs mediated potent tumor lysis, preserved a less exhausted (PD-1low and TIM-3low) and more memory-like phenotype (CD62Lhigh and CD45RAhigh), and sustained robust antitumor responses in vitro and in vivo." (PMID 41797332, 2026). "Mechanistically, EC@HNA suppressed CREB phosphorylation at Ser133, which transcriptionally repressed key stemness regulators, including CD44, CD133, and NR4A1, thereby attenuating tumor stemness and immune evasion." (PMID 41510165, 2026). "The expression of NR4A1 in metabolic pathways is expected to inhibit the abnormal metabolism of tumor cells." (PMID 40666103, 2025). "In another study, when triple negative breast cancer was treated with an NR4A1 inhibitor, it led to a decrease in the number of tumor-infiltrating Tregs and a decrease in PD-L1 expression." (PMID 40508074, 2025). "DIM-C-pPhOH was found to decrease tumor growth by inhibiting the phosphorylation of NR4A1, therefore allowing SMAD7 level to persist within the cell." (PMID 40508074, 2025). "Low expression of NR4A1 has been found in acute myeloid leukemia and chronic myelodysplastic/myeloproliferative diseases, where it exhibits tumor-suppressive effects." (PMID 40666103, 2025). "NR4A1 expression was also evaluated in a TMA with pairs of tumor and paratumor tissues from patients with BC (cohort 1)." (PMID 40164686, 2025). "NR4A1 is a potential antitumor drug target, and precise targeting of NR4A1 can induce tumor cell apoptosis and inhibit cell growth." (PMID 40666103, 2025). "As a transcription factor, the orphan nuclear receptor NR4A1 plays an oncogenic or tumor-suppressive role in tumor initiation and progression in a tumor-specific manner." (PMID 40164686, 2025). "We found that NR4A1 suppressed tumor growth in BC by antagonizing the c-Fos-mediated transcriptional activation of PRDX6, a bifunctional enzyme involved in cellular lipid and redox homeostasis." (PMID 40164686, 2025). "In concordance with this, the deletion of NR4A1 in T cells results in increased T cell effector function and enhanced tumor suppression through the increased production of IL-2 and IFN-γ and decreased PD-1 expression." (PMID 40508074, 2025). "NR4A1, a transcription factor, regulates related signaling pathways and participates in tumor cell proliferation, migration, invasion, apoptosis and immunoregulation." (PMID 40666103, 2025). "We show that PFOS and related compoundsbound the ligand binding domain (LBD) of NR4A1 and induced the growthof several cancer cell lines and enhanced tumor growth in an athymicnude mouse model." (PMID 40066943, 2025). "By developing models to predict patient risk based on immune infiltration patterns of these cell types, NR4A1 was found to play a role in regulating tumor survival and relapse." (PMID 40508074, 2025). "Tumor samples exhibited higher expression levels and a stronger staining intensity of NR4A1 compared to normal colon samples." (PMID 40508074, 2025). "The transfer of NR4A1-positive patrolling monocytes into these mice resulted in reduced metastasis via the removal of tumor cells from the lung vasculature and the recruitment of natural killer cells." (PMID 40508074, 2025). "Genetic deletion of NR4A1 in BC cells significantly promoted cellular proliferation and tumor growth." (PMID 40164686, 2025). "Cytosporone B has been shown to be an agonist of NR4A1 and can lead to the inhibition of tumor growth through the activation of apoptosis." (PMID 40508074, 2025). "Next, we performed in vivo analysis to confirm the pharmacological activation of NR4A1 in inhibiting BC growth in xenograft tumor models." (PMID 40164686, 2025). "As reviewed above, NR4A1 limits the anti-tumor activity of tumor-infiltrating CD8+ T cells, NK cells, and B cells, while enhancing the immunosuppressive functions of Tregs." (PMID 40508074, 2025).